CDH1 (cadherin 1)
Diseases named in the same sentence as CDH1 in open-access papers (continued):
Sharing a sentence is not in itself a finding about the gene and the disease.
gastric cancer (continued). "Current clinical guidelines regarding HDGC recommend prophylactic total gastrectomy for CDH1 pathogenic mutation carriers due to the observation of early gastric cancer in prophylactic gastrectomy samples from CDH1 mutation carriers 2,3." (PMID 31892987, 2020). "The cumulative life time risk for carriers of a pathogenic variant in CDH1 to develop gastric cancer is 70% for men and 56% for women." (PMID 32362280, 2020). "After adjusting for the effect of screening known HDGC families, we estimate that 6% of all advanced gastric cancers and 13% of all advanced diffuse-type gastric cancers would carry germline CDH1 mutations." (PMID 29589180, 2019). "The CDH1 gene, encoding the cell adhesion protein E-cadherin, is one of the most frequently mutated genes in gastric cancer and inactivating germline CDH1 mutations are responsible for hereditary diffuse gastric cancer syndrome (HDGC)." (PMID 31540244, 2019). "Our data demonstrates that between 2009 and 2013, 18 and 34% of Māori gastric cancer and diffuse gastric cancer cases, respectively, carried pathogenic germline CDH1 mutations." (PMID 29589180, 2019). "The main purpose of our study was to determine the prevalence of pathogenic CDH1 mutations in the Māori gastric cancer population." (PMID 29589180, 2019). "This prospective hereditary gastric cancer study has identified a non-synonymous c.1531C>T pathogenic variant in the CDH1 gene as a novel germline mutation of hereditary diffuse gastric cancer." (PMID 31600923, 2019). "In Western populations, it is estimated that 1% of all gastric cancers are caused by germline CDH1 mutations." (PMID 29589180, 2019). "It is unclear why the prevalence of pathogenic germline CDH1 mutations is so high in the Māori gastric cancer population." (PMID 29589180, 2019). "As these procedures are offered to CDH1 mutation carriers, it is likely these cases were known mutation carriers who had elected prophylactic surgery or who had foci of gastric cancer identified during endoscopic screening." (PMID 29589180, 2019). "CDH1 gene, encoding E-cadherin, is a tumor suppressor gene frequently altered in gastric cancers (GCs) of both diffuse (DGC) and intestinal (IGC) histotypes, albeit through different mechanisms." (PMID 31509966, 2019). "Overall, pathogenic germline CDH1 mutations were identified in 17/94 (18%) of the total gastric cancer cases and 17/50 (34%) of diffuse gastric cancer cases." (PMID 29589180, 2019). "As yet, the exact contribution of CDH1 mutations to the high rates of gastric cancer in the Newfoundland province is still to be determined." (PMID 29589180, 2019). "We aimed to evaluate the frequency of CDH1 germline variants and the diet/lifestyle habits in early age onset gastric cancer (EOGC, ≤ 55 years old) patients." (PMID 30895400, 2019). "In a systematic review, that compiled published series usually from regions of low incidence of gastric cancer, only 2.3% of the cases diagnosed with gastric cancer under 35 years carried pathogenic CDH1 variants." (PMID 30895400, 2019). "Methylation of the CDH1 gene promoter was also reported in about 30–40% of patients with H. pylori-associated gastric carcinoma." (PMID 31781079, 2019). "Decreased expression of CDH1 has been observed in gastric cancer with somatic mutation and methylation in the gene." (PMID 30514953, 2018). "Inactivating mutations in CDH1 are frequently observed in breast and gastric cancers with cancer type-specific mutational patterns and are associated with loss of cell-cell adhesion and increased cell motility." (PMID 29293502, 2018).
gastric cancer (continued). "Association between specific CDH1 polymorphisms with a subset of HER2-positive gastric cancer and possibly favorable prognosis has been described." (PMID 30568591, 2018). "Mutations of CDH1, the gene encoding E-cadherin, are the most common germline mutations detected in gastric cancer and underlie hereditary diffuse gastric cancer (HDGC) syndrome." (PMID 30568591, 2018). "Male CDH1 germline mutation carriers have by the age of 80 years an estimated 70% cumulative incidence of gastric cancer, females of 56% for gastric and of 42% for lobular breast cancer." (PMID 29468433, 2018). "Lifetime cumulative risk for gastric cancer in male CDH1 mutation carriers is 70% by age 80; similar risk for female CDH1 mutation carriers is 56% for diffuse gastric cancer and 42% for LBC." (PMID 29468433, 2018). "CDH1 inactivating mutations, leading to loss of protein expression, are common in gastric cancer of the diffuse histotype, while alternative mechanisms modulating E-cadherin expression characterize the more common intestinal histotype." (PMID 27861150, 2017). "This would be the expected mechanism based on previous studies in CDH1 mutated gastric cancer where abnormal cell behaviour leading to cancer depends on a two-hit model." (PMID 28550290, 2017). "The CDH1 rs5030625 (-347G->GA) decreases CDH1 expression by 10-times (P < 0.001) via inhibiting transcription factor binding and correlates with increased familial gastric cancer susceptibility." (PMID 29299175, 2017). "We previously demonstrated that activation of MET and mutations in KRAS or CDH1 were linked to the cetuximab insensitivity in gastric cancer cell lines." (PMID 29237412, 2017). "Male CDH1 mutation carriers have by the age 80 a cumulative incidence of gastric cancer of 70%, female mutation carriers a risk of 56% of gastric and 42% for lobular breast cancer." (PMID 28460635, 2017). "Search terms included: CDH1, E-cadherin, E-cadherin in cancer, gastric cancer, familial and Hereditary Diffuse Gastric Cancer, E-cadherin dysfunction, E-cadherin germline mutation, CDH1/E-cadherin missense mutation, and in vitro and in vivo functional assays." (PMID 29231860, 2017). "Of the 26,370 cases of gastric cancer expected to be diagnosed in the United States in 2016, 5 to 10 percent arise in a familiar context and about 34–45% of these are due to CDH1 germline mutations." (PMID 28460635, 2017). "Hereditary Diffuse Gastric Cancer (HDGC), an inherited condition caused because of mutation in the E-cadherin gene CDH1 is associated with increased risk of gastric cancer." (PMID 28144288, 2017). "For patients who carry a clinically significant mutation in CDH1, prophylactic total gastrectomy remains the only treatment option as a preventive measure to reduce the risk of developing gastric cancer." (PMID 27880784, 2016). "The mutations described highlight theexistence of gastric cancer cases caused by CDH1 germline mutationsin northern Brazil, although such information is frequently ignored due to theexistence of a large number of environmental factors locally." (PMID 27192129, 2016). "Since then, according to the guidelines of Oliveira and colleagues, it has been suggested that diffuse familial gastric cancer or hereditary diffuse gastric cancer is similar to gastric cancer due to the CDH1 mutation." (PMID 27127881, 2016). "Some suggest consideration of total gastrectomy in CDH1 mutation carriers at an age 5 years younger than the youngest family member who developed gastric cancer." (PMID 27512640, 2016). "Germline mutations in CDH1 cause an autosomal dominant, inherited gastric cancer susceptibility syndrome, known as Hereditary diffuse gastric cancer (HDGC, OMIM #137215)." (PMID 27880784, 2016). "Genetic testing for CDH1 germline mutations is critical for patients with early onset gastric cancer and/or a strong family history because it affects management of this disease." (PMID 27880784, 2016).
gastric cancer (continued). "Diffuse-type gastric cancer has also been associated with Early-Onset Gastric Cancer, a syndrome which occurs before 45 years of age and is linked to CDH-1 gene mutation or BRCA-1 methylation." (PMID 26379360, 2015). "We expect that the outcomes of prophylactic laparoscopic total gastrectomy will approximate the results for laparoscopic total gastrectomy for gastric cancer in larger series of patients with a CDH1 germline mutation." (PMID 26443527, 2015). "The estimated life-time risk of developing gastric cancer in carriers of a CDH1 mutation is 67% in men and 83% in women." (PMID 26396173, 2015). "In gastric cancer, it has been demonstrated that E-cadherin gene (CDH1) hypermethylation is associated with DNMT1 overexpression by EBV infection." (PMID 26032781, 2015). "As CDH1 mutations were frequent in gastric cancer (GC), several studies were performed to examine the association of CDH1 genetic polymorphisms with GC risk." (PMID 26285011, 2015). "In roughly 30% of familial gastric cancers, a germline mutation in one allele of the E-cadherin gene (CDH1) can be identified." (PMID 26396173, 2015). "The promoter region of the CDH-1 gene has been associated with DNA hypermethylation in the polymorphism −160 Increase risk of gastric cancer DNA methylation pattern of the promoter region of CDH1." (PMID 26379360, 2015). "The CDH1 somatic mutation was identical in both the primary and metastatic gastric cancer genomes, demonstrating a common genetic origin and providing strong genetic evidence that this driver had a critical role in diffuse gastric tumorigenesis." (PMID 25315765, 2014). "A CDH1 gene germline mutation was also identified in two brothers from family B who had developed an early form of gastric cancer (before 45 years of age)." (PMID 25180051, 2014). "Based on the family history of gastric cancer and the unusually young age of onset, she underwent germline CDH1 mutation testing." (PMID 25315765, 2014). "Prophylactic total gastrectomy is the recommended form of management for individuals over 20 years of age carrying a CDH1 mutation, because of their 80 % lifetime risk of developing gastric cancer and the limited value of surveillance modalities." (PMID 24838934, 2014). "Among different gastric carcinoma predisposing syndromes, hereditary gastric cancer (HDGD) is caused by a mutation of the E-cadherin gene (CDH1), which carries a more than 70% lifetime gastric cancer risk." (PMID 24688534, 2014). "Occurrence of gastric cancer in young people motivated molecular studies that identified inherited mutations in the E-cadherin/CDH1 gene described in several ethnic groups." (PMID 24707411, 2014). "For example, in the case of hereditary gastric cancer, methylation of CDH1 (which encodes the E-cadherin tumor suppressor) can function as a “second hit” and cause gastric cancer when the first allele is mutated." (PMID 24622842, 2014). "Germline mutation of CDH1 was first reported in DNA extracted from lymphocytes of two patients with gastric cancer and four obligate carriers in New Zealand." (PMID 25184143, 2014). "We find associated candidate driver genes, and identify seven novel somatic mutations in CDH1, which is a well-known gastric cancer-associated gene." (PMID 24690483, 2014). "Carriers of CDH1 germline mutations have a cumulative gastric cancer risk, before age 75, of 40–67% for men and 63–83% for women and a risk for lobular breast cancer of 39–52%." (PMID 24373500, 2013). "Statistical analysis was performed to correlate the CDH1 mutation frequency with gastric cancer incidence areas." (PMID 22225527, 2012). "In recent years, some scholars believe that prophylactic total gastrectomy on patients whose families have a gastric cancer history and who are detected CDH1 gene mutation can help to improve their prognosis." (PMID 23209465, 2012).
gastric cancer (continued). "Prophylactic gastrectomy is the only option to prevent gastric cancer in individuals with a CDH1 mutation." (PMID 23231819, 2012). "Germline loss-of-function mutations in the CDH1 gene, which encodes E-cadherin, cause human gastric cancer." (PMID 23139756, 2012). "E-cadherin genetic screenings performed in low-risk areas for gastric cancer identified a higher frequency of CDH1 germline mutations." (PMID 22225527, 2012). "Cox regression analysis revealed CDH1 methylation in PPW was an independent risk factor for gastric cancer patients, with a remarkable decrease in DFS after postoperative 30 months." (PMID 22514028, 2012). "Search terms included CDH1, E-cadherin, germline mutation, gastric cancer, hereditary, familial and diffuse histotype." (PMID 22225527, 2012). "The goal of this study was to assess the worldwide frequency of CDH1 germline mutations in gastric cancers coming from low- and high-risk areas." (PMID 22225527, 2012). "For both men and women, CDH1 mutation carriers have a cumulative risk of gastric carcinoma by 80 years of age of 80%, with a mean age at diagnosis of 40 years." (PMID 23231819, 2012). "The finding that CDH1 mutation frequencies are extremely different in high and low-risk GC zones confirms that gastric carcinoma presents various clinico-pathologic and molecular features." (PMID 22225527, 2012). "The total frequency of CDH1 mutations in exons 2-16 that were observed in our study was 9% for all investigated tumours and 13% when only diffuse and mixed-type gastric carcinomas were taken into account." (PMID 22152101, 2011). "The CDH1 mutation carries a high penetrance with carriers of germline mutations having an estimated lifetime risk of 67% in men and 83% in women to develop gastric carcinoma." (PMID 21331337, 2011). "The penetrance for gastric cancer among individuals with a CDH1 mutation is estimated to be about 40%." (PMID 19888225, 2010). "CDH1 promoter hypermethylation frequently occurs in gastric carcinomas with a diffuse histotype and is significantly associated with down-regulated E-cadherin expression." (PMID 21203466, 2010). "One reason is that the incidence of familial gastric cancer or early-onset gastric cancer is relatively low, and the other is that selection in regard to CDH1 promoter polymorphisms and CDH1 expression was necessary in this study." (PMID 19671196, 2009). "Since there is a CDH1 haplotype associated with increased gastric cancer risk and the haplotype contains the -161A allele, the genotyping method will be also valuable for evaluating the risk of gastric cancer." (PMID 19671196, 2009). "We tried investigating the allele-specific methylation status of the CDH1 promoter in two groups of gastric cancers, a familial gastric cancer or early-onset gastric cancer group and a sporadic gastric cancer group." (PMID 19671196, 2009). "Among these mechanisms that cause CDH1 inactivation, inactivating germline mutations are the only genetic mechanism which is inherited in gastric cancer." (PMID 19671196, 2009). "As a result, 18 patients with sporadic gastric cancer showing loss of CDH1 protein expression were ultimately chosen from a total of 159 patients." (PMID 19671196, 2009). "Somatic CDH1 mutations have been found in about 50% of diffuse-type gastric cancers, and germline CDH1 mutations have been reported in familial gastric cancers in several ethnic groups." (PMID 19671196, 2009). "Some genetic alterations are exclusive of given subtypes of gastric carcinomas, as exemplified by CDH1 mutations in diffuse gastric carcinomas." (PMID 19156142, 2009). "AA425217 was published as a significant gene in colorectal cancer, and 16q22.1, where AA425217 is located, is a region that includes CDH1, which encodes cell-cell adhesion protein and is expressed in gastric cancer and lobular breast cancer." (PMID 18554423, 2008).
gastric cancer (continued). "This retrospective single-center cohort study included all patients undergoing minimally invasive total gastrectomy (laparoscopic or robot-assisted) for gastric cancer or prophylaxis in CDH1-mutated patients at Karolinska University Hospital (Stockholm, Sweden) from 1 January 2015 to 31 August 2025." (PMID 42156604, 2026). "In addition to the gastric cancer risk, individuals with CDH1 mutations also face a heightened risk of LBC, with estimates ranging from 39% to 52%." (PMID 40585607, 2025). "Among the genetic factors that influence gastric cancer, hereditary diffuse gastric cancer (HDGC) is a significant hereditary syndrome characterized by a high risk of developing gastric cancer, primarily due to mutations in the CDH1 gene, which encodes E-cadherin." (PMID 40585607, 2025). "Importantly, clinical-pathological evaluation demonstrated that patients with genomically stable gastric cancer—characterized by CDH1 loss and predominantly manifesting as DGC—showed significantly attenuated responses to immunotherapy." (PMID 40817248, 2025). "This disparity may be attributed to differences in genetic background, as populations from various ethnic or geographic regions may exhibit different genetic predispositions affecting the correlation between CDH1-160C>A polymorphism and gastric cancer risk." (PMID 40416864, 2025). "Notably, individuals with a family history of gastric cancer exhibit an incidence rate two to three times higher particularly in families with germline CDH1 mutations." (PMID 40371231, 2025). "However, environmental factors such as H. pylori infection can further influence the risk and progression of gastric cancer in individuals with CDH1 mutations." (PMID 40585607, 2025). "Thus, case reports of SRC detection by endoscopy or diagnosis of Stage IA gastric cancer in children with CDH1 variants should be interpreted with caution." (PMID 39760880, 2025). "In addition to gastric cancer risks, female CDH1 mutation carriers face a significant risk of developing LBC." (PMID 40585607, 2025). "In addition, gastric cancer patients were likely to have mutations in CDH1, ACTRT1, GANAB, and CDH10 genes in the High-CCDC80 group." (PMID 38872096, 2024). "For CDH1 variant carriers, the long-term sequelae of total gastrectomy, not just acute operative risk, should be given equal consideration as the chance of developing advanced gastric cancer." (PMID 37903316, 2024). "Indeed, many clinical studies have revealed that the loss of CDH1 is an independent marker for gastric cancer progression." (PMID 38200154, 2024). "Treatment with FAK inhibitors has demonstrated significant efficacy against CDH1-deficient gastric cancer, characterized by downregulated E-cadherin and damaged membrane E-cadherin/β-catenin protein complexes a, resulting in reduced sensitivity of tumor cells to chemotherapy." (PMID 38410129, 2024). "Another Yale-based study reported a cumulative risk of developing gastric cancer of 37.2% for men and 24.4% for women in a cohort of 113 unselected CDH1 mutation carriers (and 476 family members) who had genetic testing due to familial clustering of various cancers." (PMID 35499650, 2023). "Given the abundance of gastric cancers bearing simultaneous loss of CDH1 expression and CDH3 upregulation, we tested whether depleting CDH1 would trigger CDH3 upregulation." (PMID 37372088, 2023). "Overall, the cumulative incidence of gastric cancer by age 80 years for pathogenic CDH1 variant carriers is now estimated at 37 to 42% for men and 25 to 33% for women, about half of the initial estimation described before the advent of high-throughput sequencing." (PMID 37761816, 2023). "Of the 33.3% of IGs diagnosed with gastric cancer in our cohort, only 4.8% were found to be harboring mutation in the CDH1 gene, whereas this ratio was comparatively high in the case of CGs (55% diagnosed with gastric cancer, 30% carrying a mutation in the CDH1 gene)." (PMID 36831145, 2023).